CYP4Z1 (cytochrome P450 family 4 subfamily Z member 1)
Diseases named in the same sentence as CYP4Z1 in open-access papers (continued):
Sharing a sentence is not in itself a finding about the gene and the disease.
breast carcinoma (continued). "Weak to no CYP4Z1 expression was exhibited in cervical and breast cancer tissues treated with a mixture of CYP4Z1 primary antibody and blocking peptide." (PMID 34590601, 2021). "Moreover, the ceRNA network between CYP4Z1 and CYP4Z2P led to progression of breast cancer, including suppressed apoptosis and induced tamoxifen resistance." (PMID 32185172, 2020). "While there have been limited studies evaluating CYP4Z1 expression in breast cancer, none has attempted to explore the relationship between the expression of CYP4Z1 and key molecules involved in breast cancer pathogenesis." (PMID 33144882, 2020). "The pattern of CYP4Z1 expression and involvement of lymph node metastasis in breast cancer has not been studied previously." (PMID 33144882, 2020). "The CYP4Z1 30UTR could limit migration and EMT of breast cancer cells acting as a ceRNA for E-cadherin, and MicroRNA-17 induces EMT persistent with the cancer stem cell phenotype by controlling CYP7B1 expression in colon cancer." (PMID 31662772, 2019). "Notably, a qRT-PCR assay of clinical samples showed that both six2 and CYP4Z1 expression and six2 and CYP4Z2P expression were positively correlated in breast cancer tissues (P < 0.001)." (PMID 30832689, 2019). "Notably, the expression of CYP4Z1 and CYP4Z2P displayed a positive correlation in clinical breast cancer samples (P < 0.001)." (PMID 30832689, 2019). "The observation that MCF7 breast cancer cells, in contrast to nontumorigenic MCF10A cells, display CYP4Z1 on their surface might indicate its usefulness in breast cancer immunotherapy." (PMID 41020804, 2025). "Moreover, overexpression of CYP4Z1 and/or CYP4Z2P in breast cancer cells may promote transcriptional activity of oestrogen receptors, stemness, and tamoxifen resistance." (PMID 34590601, 2021). "This change in fatty acid levels was concordant with the hypothesis that CYP4Z1 is responsible for the metabolism of myristic and lauric acids, as well as conversion of arachidonic acid to 20-HETE, resulting in tumour angiogenesis and growth of breast cancer." (PMID 33144882, 2020). "Importantly, the expression of six2, CYP4Z1, and the pseudogene CYP4Z2P was negatively correlated with the OS of breast cancer patients, and the expression of these genes was positively correlated with one another, underscoring the critical roles of this regulatory axis in breast cancer progression." (PMID 30832689, 2019).
breast tumor (4 papers, 2017 to 2025). "The expression of CYP4Z1 and the pseudogene CYP4Z2P was significantly increased in breast tumor tissues, which is consistent with our previous work in which CYP4Z1 and pseudogene CYP4Z2P expression was detected in clinical samples." (PMID 30832689, 2019). "CYP4Z1 was differently expressed across the panel of breast tumours." (PMID 33144882, 2020). "Additionally, understanding the biological mechanism behind CYP4Z1 activation could help in the design of prodrugs that are selectively activated in breast tumor tissue, minimizing systemic side effects of chemotherapy." (PMID 41020804, 2025). "The mean expression (in reads per million, or RPM) of CYP4Z1 in adjacent normal tissue (all matched normal tissue samples at TCGA combined), BRCA tissue (all racial groups combined), and separately for CA, AS, and AA breast tumor tissue was 36.9, 92.2, 101, 52.7, and 63.6, respectively." (PMID 28684774, 2017).
ovarian carcinoma (4 papers, 2020 to 2023). A malignant neoplasm originating from the surface ovarian epithelium. "Such a significant association has been reported in many studies linking CYP4Z1 expression with poor patient survival and connecting it to aggressive characteristics of cancers such as breast, colon, prostate, cervical, and ovarian cancers." (PMID 36143940, 2022). "The analysis revealed that there was a significant association between CYP4Z1 expression and ovarian cancer patients’ survival rate (p = 0.002)." (PMID 36143940, 2022). "As there are no functional studies assessing the mechanistic role of CYP4Z1 in the progression of ovarian cancer, several studies have linked CYP4Z1 with cancer development in general." (PMID 36143940, 2022). "Therefore, the current study aims to investigate the frequency of CYP4Z1 in various pathological subtypes of ovarian cancers and its association with histopathological features, as well as prognosis." (PMID 36143940, 2022). "Interestingly, CYP4Z1 expression was associated with a poor survival rate of ovarian cancer patients and identified as an independent factor for overall survival." (PMID 36143940, 2022). "The hypomethylated CYP4X1 and CYP4Z1 genes together are presumed to be involved in human breast and ovarian cancers." (PMID 38264209, 2023). "There was a marked difference in the CYP4Z1 expression between normal tissue samples and different histopathological subtypes of ovarian cancer." (PMID 36143940, 2022). "The results showed that 79% of the ovarian cancers investigated had CYP4Z1 expression, and the expression was confined to tumor cells." (PMID 36143940, 2022). "This differential in CYP4Z1 expression was able to allow discrimination between benign, primary, and metastatic breast, colon, and ovarian cancers." (PMID 36143940, 2022). "Significantly, CYP4Z1 expression was correlated with shorter survival and connoted a poor prognosis for ovarian cancer patients." (PMID 36143940, 2022). "In a preliminary study utilizing a small number of samples, CYP4Z1 expression was successfully characterized in certain cancers, including ovarian cancer." (PMID 36143940, 2022). "In the current study, the CYP4Z1 enzyme’s role as a clinicopathological marker in ovarian cancer was assessed." (PMID 36143940, 2022). "The results showed that CYP4Z1 expression was the only independent predictor of poor prognosis of ovarian cancer patients (p = 0.01; HR= 1.177, 95% CI = 1.040–1.332)." (PMID 36143940, 2022). "Materials and Methods: Immunohistochemistry was used to characterize CYP4Z1 expression in 192 cases of ovarian cancers along with eight normal ovarian tissues." (PMID 36143940, 2022). "As only one study has explored CYP4Z1 expression in a small cohort of ovarian cancers, the current study has identified CYP4Z1 expression in a wide range of different histopathological types of ovarian cancers." (PMID 36143940, 2022). "In an initial screening that used a limited number of tumor samples, we identified selective expression of CYP4Z1 in various types of cancers, including ovarian cancer." (PMID 36143940, 2022). "In profiling the expression of CYP enzymes in breast, ovary and colon cancers, CYP4Z1 was overexpressed in all tumours examined compared to normal tissues, and its expression in ovary cancer was suggested to be a biomarker for prognosis." (PMID 33144882, 2020). "Furthermore, our findings are in line with the Human Protein Atlas data on CYP4Z1 transcription profiling in ovarian cancer." (PMID 36143940, 2022). "Therefore, the current study aims to assess CYP4Z1 expression in different subtypes of ovarian cancers." (PMID 36143940, 2022). "Overall, the CYP4Z1 enzyme could be used as a biomarker and potential target for the discovery and development of novel therapies for ovarian cancer." (PMID 36143940, 2022). "When compared to normal ovarian tissues, ovarian cancers have high CYP4Z1 mRNA levels." (PMID 36143940, 2022).
ovarian carcinoma (continued). "Our results imply that CYP4Z1 has a possible role in ovarian cancer progression and metastasis." (PMID 36143940, 2022). "Importantly, this trend in the differential expression of CYP4Z1 was identified in many cancer types, including ovarian cancer." (PMID 36143940, 2022). "Importantly, CYP4Z1 expression was considered an independent prognostic biomarker for prostate and ovarian cancers." (PMID 33144882, 2020). "Furthermore, CYP4Z1 expression was prevalent in all ovarian cancer pathological subtypes." (PMID 36143940, 2022). "Despite the lack of functional research examining CYP4Z1’s mechanistic role in the development of ovarian cancer, various investigations have connected CYP4Z1 to the tumorigenesis process." (PMID 38001897, 2023). "A distinct expression of CYP4Z1 was characterized in all pathological subtypes of ovarian cancers in comparison with the lack of expression in normal ovarian tissues." (PMID 36143940, 2022). "However, there are no data on CYP4Z1 expression in a large cohort of different pathological subtypes of ovarian cancers." (PMID 36143940, 2022). "In addition, immunostaining was not identified in ovarian cancer specimens treated with a mixture of blocked CYP4Z1 antibodies." (PMID 36143940, 2022).
lymph node metastasis (3 papers, 2020 to 2022). "Univariate analysis revealed that patient survival was strongly associated with CYP4Z1 expression, tumor stage, depth of invasion, and lymph node metastasis (p < 0.05)." (PMID 36143940, 2022). "Further significant associations were found between CYP4Z1 expression and tumour invasion and lymph node metastasis." (PMID 34590601, 2021). "CYP4Z1 expression was significantly associated with the histological grade and status of lymph node metastasis." (PMID 33144882, 2020). "In a univariate Cox regression analysis, CYP4Z1 expression, histological stage, tumor depth of invasion, and lymph node metastasis had a significant influence on the overall survival rate (p < 0.05)." (PMID 36143940, 2022). "In univariate analysis, CYP4Z1 expression, histological stage, tumour invasion, and lymph node metastasis were significantly correlated with overall survival, with p-values of 0.002, 0.007, 0.008 and 0.003, respectively." (PMID 34590601, 2021). "Univariate analysis showed that CYP4Z1 expression, tumour stage, lymph node metastasis, and tumour invasion were significantly correlated with patient survival (p < 0.05)." (PMID 34590601, 2021). "The relationship between the CYP4Z1 expression and status of lymph node metastasis was also investigated." (PMID 33144882, 2020). "Despite the small number of patients with lymph node metastasis, a high rate of lymph node metastasis was seen in CYP4Z1-positive patients." (PMID 33144882, 2020).
prostate carcinoma (3 papers, 2020 to 2021). A carcinoma that arises from epithelial cells of the prostate gland. "Our observations support previous studies where the CYP4Z1 expression profile was assessed in breast, ovary, colon and prostate cancers." (PMID 33144882, 2020). "Moreover, the elevated CYP4Z1 expression was correlated with a higher mortality rate in patients with prostate cancer and was suggested as an independent prognostic marker for prostate cancer." (PMID 33144882, 2020).
colon cancer (2 papers, 2019 to 2021). "Moreover, we recently identified a similar fashion of CYP4Z1 differential expression in bladder and colon cancers (data not published)." (PMID 34590601, 2021).
adenocarcinomas of colon (1 paper, 2020). "Nevertheless, several types of tumours demonstrated CYP4Z1 expression, including carcinomas of adrenal cortex, squamous cells of oesophagus, lung and cervix, astrocytoma, melanoma and seminoma, as well as adenocarcinomas of colon, ovary, prostate and endometrium." (PMID 33144882, 2020).
adenoma (1 paper, 2020). A neoplasm arising from the epithelium. "In benign tumours, only breast adenoma showed weak immunoreactivity for CYP4Z1, while it was negative for the adenomas of adrenal gland, small intestine, colon, salivary gland, ovary and thyroid." (PMID 33144882, 2020).
astrocytoma (1 paper, 2020). "CYP4Z1 was found to be expressed in carcinomas of adrenal cortex, squamous cell of oesophagus, lung and cervix, as well as seminoma, astrocytoma, melanoma and lastly endometrial adenocarcinoma." (PMID 33144882, 2020). "Interestingly, several tumour entities showed prominent expressions of CYP4Z1, including carcinomas of adrenal cortex, squamous cells of oesophagus, lung and cervix, as well as seminoma, astrocytoma, melanoma and lastly endometrial adenocarcinoma." (PMID 33144882, 2020).
bladder cancers (1 paper, 2021). "Our study is the first to present convincing evidence of strong CYP4Z1 expression in different pathological subtypes of bladder cancer compared with low expression in corresponding normal tissues." (PMID 33692504, 2021). "CYP4Z1 and CYP1B1 proteins are expressed at much higher rate in bladder cancer than in corresponding normal tissues." (PMID 33692504, 2021). "The expression profiles of CYP4Z1 and CYP1B1 suggest that both enzymes have the potential to be biomarkers or targets for novel anticancer therapy for bladder cancer." (PMID 33692504, 2021). "By using immunohistochemistry, expression of CYP4Z1 and CYP1B1 was evaluated in a panel of different types of bladder cancer, and the enzymes’ relation to histopathological features were assessed." (PMID 33692504, 2021). "The current study investigated the CYP4Z1 and CYP1B1 expressions across a panel of different types of bladder cancer to confirm the hypothesis that CYP4Z1and CYP1B1 expressions may present novel opportunities for the development of new treatments for bladder cancer." (PMID 33692504, 2021). "Results showed an increased expression of CYP4Z1 (54.3%) and CYP1B1 (76.9%) in the majority of bladder cancers compared to weak or lack of expression of both enzymes in normal tissues." (PMID 33692504, 2021).
breast adenocarcinoma (1 paper, 2020). "As expected, all specimens of breast adenocarcinoma revealed the most frequent expression of CYP4Z1." (PMID 33144882, 2020).
breast ductal carcinoma (1 paper, 2025). "The analysis of the CYP expression profile in the ER(+) T47D cell line, also derived from ductal carcinoma, revealed the presence of CYP4Z1." (PMID 41020804, 2025). "As CYP4Z1 is considered an EET synthase, it was therefore not surprising that the major products of internal oxidation of arachidonic acid (AA) in breast ductal carcinoma T47D cells engineered to express CYP4Z1 were derivatives 14,15-EET and 14,15-dihydroxy eicosatrienoic acid." (PMID 41020804, 2025).
cervical cancer (1 paper, 2021). A primary or metastatic malignant neoplasm involving the cervix. "CYP4Z1 expression was associated with poor survival rate and identified as an independent factor for poor prognosis in cervical cancer patients, along with tumour stage." (PMID 34590601, 2021). "As the current study was the first investigating the CYP4Z1 expression in cervical cancers, we found that 55% of the tumours expressed CYP4Z1, where the expression in each tumour sample was specifically confined to tumour cells." (PMID 34590601, 2021). "Low to high CYP4Z1 mRNA levels were identified in cervical cancers compared to normal cervix tissues." (PMID 34590601, 2021). "This was the first study indicating a significant correlation between CYP4Z1 expression and cervical cancer patients’ survival." (PMID 34590601, 2021). "Our recent initial screening has identified overexpression of CYP4Z1 in a small number of tumour samples for each type of human tumour including cervical cancer." (PMID 34590601, 2021). "In a recent pilot study, we detected CYP4Z1 as being strongly expressed in a small number of cervical cancers." (PMID 34590601, 2021). "Human protein atlas results on CYP4Z1 mRNA profiling in 291 cervical cancer patients demonstrated that 93 (28.5%) patients had elevated expression, while the remaining 208 patients (71.5%) showed low expression." (PMID 34590601, 2021). "The high frequency of CYP4Z1 expression in cervical cancer is consistent with the findings of our earlier initial screening." (PMID 34590601, 2021). "On this basis, our observations were expanded to investigate aberrant CYP4Z1 expression in a large number of tissues including cervical cancers and the normal cervix, and to explore its relation to demographic and clinicopathologic features as well as patient survival." (PMID 34590601, 2021). "Interestingly, CYP4Z1 expression was significantly correlated with shorter survival times of cervical cancer patients." (PMID 34590601, 2021). "As Cytochrome4Z1 (CYP4Z1) is overexpressed in many tumours, its expression in cervical cancer is unknown." (PMID 34590601, 2021). "Overall, the discovery of novel biomarkers probably CYP4Z1 may hold promise for cervical cancer management." (PMID 34590601, 2021). "The role of the CYP4Z1 enzyme as a prognostic marker in cervical cancer was assessed in this study." (PMID 34590601, 2021). "In multivariate analysis, CYP4Z1 expression was found to be an independent prognostic predictor of poor cervical cancer patient survival (p = 0.034; HR 1.113, 95% CI = 1.059–1.743), along with another prognostic factor, histological stage (p = 0.023; HR 7.384, 95% CI = 3.318–11.381)." (PMID 34590601, 2021). "Importantly, CYP4Z1 expression was significantly correlated with a shorter survival rate and poor prognosis of cervical cancer patients." (PMID 34590601, 2021). "Moreover, our results agree with CYP4Z1 transcription profiling in cervical cancers shown by the Human Protein Atlas." (PMID 34590601, 2021). "Therefore, there remains a question about CYP4Z1 protein expression profile in cervical cancers relative to normal cervix tissues." (PMID 34590601, 2021). "Therefore, the implications of this observation have been taken to fully characterise the CYP4Z1 expression in a large cohort of cervical cancers." (PMID 34590601, 2021). "CYP4Z1 expression was identified in 55% (55 cases) of cervical cancers." (PMID 34590601, 2021). "Therefore, the present study aimed to evaluate CYP4Z1 expression in cervical cancers." (PMID 34590601, 2021). "However, the link between the CYP4Z1 enzyme and cervical cancer development remains elusive." (PMID 34590601, 2021). "Unique CYP4Z1 expression was identified in 55% of cervical cancers compared to negative expression in normal cervix tissues." (PMID 34590601, 2021).
endometrioid adenocarcinoma (1 paper, 2021). An adenocarcinoma characterized by the presence of malignant glandular epithelial cells resembling endometrial cells. "All patients with adenocarcinoma and endometrioid adenocarcinoma exhibited CYP4Z1 expression." (PMID 34590601, 2021).
metastatic tumours (1 paper, 2020). "The present study has examined the expression of CYP4Z1 in a panel of different human tissues, including most of the common benign, malignant and metastatic tumours." (PMID 33144882, 2020).
papillary adenocarcinoma (1 paper, 2022). A morphologic variant of adenocarcinoma. "A high frequency of CYP4Z1 expression was exhibited in papillary adenocarcinomas (serous and mucinous) compared to that in other pathological subtypes." (PMID 36143940, 2022). "However, papillary adenocarcinoma tumors of either serous or mucinous subtypes showed discriminable expression of CYP4Z1 from other histopathological subtypes (91.7%, 44 cases and 100%, 14 cases, respectively)." (PMID 36143940, 2022).
Parkinson (1 paper, 2025). "In a Parkinson’s progression markers initiative cohort, CYP4Z1 exhibited a total of 781 SNPs, with only a small number showing a significantly increased occurrence in PD patients compared to healthy controls." (PMID 41026459, 2025).
squamous cell carcinoma (1 paper, 2021). A carcinoma arising from squamous epithelial cells. "As the squamous cell carcinoma was the major pathological subtype in this study (95 cases), the overall survival and prognostic utility of CYP4Z1 expression in squamous cell carcinomas were analysed." (PMID 34590601, 2021). "Of positive patients, CYP4Z1 was expressed in 50% (50 cases) of patients with squamous cell carcinoma." (PMID 34590601, 2021).